AKT1 (AKT serine/threonine kinase 1)
Diseases named in the same sentence as AKT1 in open-access papers (continued):
Sharing a sentence is not in itself a finding about the gene and the disease.
breast cancer (continued). "Further studies will show whether targeting specifically the expression of AKT1m is a suitable strategy to downregulate AKT1 in breast cancer cells without a complete ablation of the ubiquitously expressed transcripts in normal tissues." (PMID 24628780, 2014). "Evaluation of Akt1, Akt2 and Akt3 revealed that Akt1 and Akt2 can be detected in both WT mammary tissue and mammary tumors while Akt3 could not be detected in either WT mammary tissue or mammary tumors." (PMID 23919516, 2013). "This is further exemplified in breast cancer mouse models: while overexpression of AKT1 accelerates ErbB-2 mediated mammary tumorigenesis and suppresses tumor invasion, overexpression of AKT2 markedly increases the incidence of pulmonary metastases in breast cancer." (PMID 22666248, 2012). "This may be due to different biological effects of Akt1 and Akt2 in HER2-positive breast cancer." (PMID 22842582, 2012). "In addition, a lack of BRCA1 activates the AKT1 pathway by causing disappearance of the PTEN protein, which is observed in 82% of hereditary breast cancers linked to BRCA1." (PMID 21321378, 2010). "Additionally, it was covered by insurance in Japan in May 2024, and the detection of PIK3CA, AKT1, and PTEN alterations by FoundationOne CDx is a companion diagnosis for the use of capivasertib in HR-positive HER2-negative advanced breast cancer with PIK3CA, AKT1, or PTEN alterations." (PMID 39466567, 2025). "However, AKT1 inhibitors have not yet been approved for the treatment of breast cancers." (PMID 34885114, 2021). "In addition, MK2206 at a low dosage enhance breast cancer metastasis in a mouse model of lung metastasis, while an inhibitor of EGFR tyrosine kinase Gefitinib could potentially suppress breast cancer metastasis induced by Akt1 inhibition." (PMID 30445978, 2018). "Interestingly, bigenic expression of activated MMTV-Neu and constitutively active Akt1 under MMTV promoter results in accelerated tumor onset but suppressed metastasis, implicating that the malignancy-promoting function of Akt1 in mammary cancer is mainly targeting the primary tumor." (PMID 24709902, 2014). "Although numerous publications have discussed the signal cascade and the role of PI3K and the various AKT isoforms in breast cancer, crosstalk between ARHGAP29 and AKT1 signaling has not yet been reported." (PMID 33291460, 2020). "Ablation of AKT1, but not of AKT2, also promotes EMT of breast cancer cells especially after TGF-β stimulation by decreasing the amounts of the miR-200 family." (PMID 31752925, 2019). "In contrast to the patient data, AKT1 mRNA levels were not affected in the MB231 and MCF7 human breast cancer cell lines after 24 hrs chemotherapy exposure." (PMID 28476032, 2017). "On the contrary, AKT1, but not AKT2 and AKT3, inhibited EMT in breast cancer, depressing Twist1 activation." (PMID 27231938, 2016). "These experiments are particularly important as activated Akt1 does not induce tumors in mice but overexpression of ILK does, and ILK has been shown to play a critical role in MMTV-Neu mouse mammary tumors." (PMID 21646685, 2011). "Akt1, but not Akt2, was shown to promote breast cancer cell proliferation by upregulating cyclin D1 and S6 (a downstream target of mTORC1) in IBH-6 and T47D breast cancer cells." (PMID 34298660, 2021). "HER-2-positive breast cancer cells that are sensitive to HER-2-targeting agents can be eradicated by treatment; for TN and luminal breast cancers, however, the residual tumor cell targets other than AKT1 are not known." (PMID 33672204, 2021). "However, inducible systemic Akt1 deletion after tumour initiation, but not cell-autonomous Akt1 ablation, inhibited metastasis in HER2-enriched mouse models of breast cancer by impairing neutrophil mobilisation." (PMID 33276499, 2020).
breast cancer (continued). "However, there is growing evidence that the different isoforms AKT1, AKT2 and AKT3 have non-redundant and partly opposing effects in tumorigenesis, making pan-AKT inhibition in breast cancer inappropriate." (PMID 31752925, 2019). "Although, AKT1, AKT2 and AKT3 share a high homology, are activated and regulated by the same upstream mechanisms and share a wide range of substrates, the three isoforms exert non-redundant and partly opposing roles in breast cancer." (PMID 31752925, 2019). "The decrease of AKT1 expression was observed in basal-like and HER2 negative breast tumor, which could benefit for diagnosis and targeted therapy of basal-like breast cancer based on subtype." (PMID 28301567, 2017). "However, in endocrine‐resistant breast cancer, STING agonist monotherapy failed to active the STING signaling, due to the positive feedback of inactivated STING signaling and hyperactivated AKT1 strengthening the suppression of cGAS‐STING pathway by AKT1." (PMID 39023171, 2024). "However, the results revealed that knockdown of Akt1 in MCF-7 and MDA-MB-231 cells failed to promote the mRNA expression of EGFR, suggesting that additional target is contributing to the overexpression of EGFR in Akt1 impaired breast cancer cells." (PMID 30445978, 2018).
lung carcinoma (587 papers, 2002 to 2026). "Lung cancer differentiation, lymph node metastasis, and stage are closely associated with AKT1 expression." (PMID 40510163, 2025). "The frequency of AKT1 (E17K) mutation in lung cancer is rare; it is approximately 0.6–5.5% in lung cancer patients." (PMID 39329938, 2024). "In another genomic study of BM of various origin, several potentially actionable genomic alterations were associated with lung cancer BM, including AKT1, AURKA, CDK6, EGFR, MEK1, MET, and PIK3CA gene amplifications and CDKN2A deletions." (PMID 36561283, 2022). "Among the five PRlncRNAs included in the signature, the lncRNA PICART1 is closely associated with the suppression of lung cancer cell proliferation by targeting the AKT1 and JAK2/STAT3 signaling pathways." (PMID 35739504, 2022). "AKT1 is frequently overexpressed in malignant tumors such as gastric cancer and lung cancer, and is associated with sustained proliferation of tumor cells." (PMID 31160577, 2019). "Using our transgenic mouse model of IGF-IR driven lung cancer, we found that loss of Akt1 suppressed while loss of Akt2 augmented, lung tumor development." (PMID 26654940, 2016). "The hotspot AKT1E17K mutation in the pleckstrin homology domain of AKT1 occurs in approximately 0.6–2% of human lung cancers." (PMID 26859676, 2016). "In lung cancer a somatic mutation in the pleckstrin homology (PH) domain of AKT1 that results in glutamic acid to lysine substitution at residue 17 (E17K) was reported with overall frequency of 0.6–2%." (PMID 26859676, 2016). "AKT1 rs2494752 was selected because that it was reported to be associated with chemotherapy response in advanced non‐small cell lung cancer among a Chinese Population 25, and it is also a SNP in the transcription factor‐binding site of the AKT1 gene." (PMID 26828791, 2016). "The hotspot E17K mutation in the pleckstrin homology domain of AKT1 occurs in approximately 0.6–2% of human lung cancers." (PMID 26053093, 2015). "The AKT1 (E17K) mutation has been reported in some tumour types (breast, colorectal, ovarian and lung cancers), and it is of interest which tumour types other than those possess the E17K mutation." (PMID 19491896, 2009). "Biologically, previous studies have shown that APC is associated with cancer recurrence, and AKT1 are associated with several different cancers, such as breast, colorectal, and lung cancers." (PMID 19956614, 2009). "AKT1 amplification was initially identified in gastric cell lines and has shown to be associated with cisplatin resistance in lung cancer cells through the mTOR pathway." (PMID 18611285, 2008). "We sought to determine if the recently identified activating mutation (E17K) in AKT1, which was initially detected in breast, colorectal, and ovarian cancers, and more recently in lung cancer, occurs in melanoma tumours and cell lines." (PMID 18813315, 2008). "Finally, altered PTEN expression is associated with poor prognosis in lung cancer, frequently characterized by aberrant AKT activation due to loss of PTEN or PIK3CA/AKT1 activating mutations, often leading to treatment resistance." (PMID 40710199, 2025). "AKT1 amplification was shown to be associated with CDDP resistance in human lung cancer cells." (PMID 36564761, 2022). "AKT1 has been identified as a candidate driver gene in adenocarcinoma and has been identified as an important regulator of invasion and metastasis of lung cancer cells having KRAS or EGFR mutations." (PMID 35932303, 2022). "In our previous study, by pharmacological exploration, we have found that tumor growth can be inhibited by cell cycle inhibition and antiangiogenesis with the VEGFA epidermal growth factor receptor CASP3 AKT1 CCND1 associated with the prognosis of lung cancer patients." (PMID 33628320, 2021). "In this manuscript, we sought to determine whether this AKT1 variant is a bona-fide activating mutation and plays a role in the development of lung cancer." (PMID 26053093, 2015).
lung carcinoma (continued). "In lung cancer AKT1 mutations are rare, with overall reported frequency of 0.6–2%." (PMID 26053093, 2015). "The PI3K/AKT-1 pathway has been implicated in WT1 signaling in lung cancer." (PMID 25929687, 2015). "We report that Akt1 ablation inhibits the incidence and development of lung tumors, Akt2 deficiency markedly accelerates lung tumor initiation and Akt3 ablation slightly enhances tumor progression in this mouse model of lung cancer." (PMID 24722238, 2014). "Although, AKT1 mutations are rare in lung cancer (1.9%), the oncogenic properties of E17K mutaions might also contribute to the development of a fraction of lung carcinoma with squamous histotype (5.5%)." (PMID 22928112, 2012). "AKT1 amplification was shown to be a cause of cisplatin resistance in lung cancer cells." (PMID 18611285, 2008). "The AKT1 E17K mutation is very rare in lung cancer and might be associated with tumorigenesis in squamous cell carcinoma." (PMID 18611285, 2008). "Previously, the AKT1 rs3803304 polymorphism has been demonstrated to also influence susceptibility, disease progression or clinical outcome of head and neck squamous cell carcinoma, lung carcinoma and esophageal carcinoma, indicating its major functional and clinical implications." (PMID 33112820, 2020). "AKT1 regulates cell proliferation, survival, and metabolism, while mutations in EGFR increase lung cancer sensitivity to tyrosine kinase inhibitor therapy." (PMID 39796173, 2025). "According to our results, AKT1 expression was shown to be significantly increased in Odo A-treated lung cancer cells (p < 0.05)." (PMID 40141789, 2025). "In brief, preclinical evidence reveals that targeting IL-6, STAT3, MAPK3, or AKT1 provides an effective way to suppress lung cancer." (PMID 39258670, 2024). "AKT1 was found to be a key pathway target for antitumor activity, which is closely related to the prognosis and differentiation grade of lung cancer." (PMID 38571356, 2024). "Conversely, Hsp90aa1 is overexpressed in patients with lung cancer, and downregulation of Hsp90aa1 promotes cell apoptosis and inhibits proliferative ability by inhibiting the AKT1/ERK pathway." (PMID 39220589, 2024). "PI3K/AKT is over-activated in NSCLC cells, and overexpression of AKT1 leads to cisplatin resistance in lung cancer cells, while inhibition of AKT1 expression can reverse multi-drug resistant lung adenocarcinoma cell (A549/CDDP) resistance to cisplatin." (PMID 38200409, 2024). "Kaempferol induced apoptosis in lung cancer A549 cells by inactivating AKT1, downregulating the expression levels of Bcl-2 and Bcl-xL, upregulating the expression levels of Bax, and cleaving PARP." (PMID 38606171, 2024). "Western blot analyses revealed pronounced reduction of E-cadherin and NCAM in the Akt3-kd cells, whereas Akt1 and Akt2 depletion upregulated E-cadherin, especially in H23 lung carcinoma cells." (PMID 38291468, 2024). "The expression and transcription of HSP90AA1 as well as the activity of the AKT1/ERK pathways were found to be higher in the tissues of lung cancer patients." (PMID 37764733, 2023). "Kaempferol Suppresses Transforming Growth Factor-β1–Induced Epithelial-to-Mesenchymal Transition and Migration of A549 Lung Cancer Cells by Inhibiting Akt1-Mediated Phosphorylation of Smad3 at Threonine-179 (Jo, Park, Choi, Jeon, & Kim, 2015)." (PMID 37533633, 2023). "PRMT5 has also been shown to promote metastasis of lung cancer cells by activating the AKT1 and ERK signaling pathways." (PMID 37400960, 2023). "Kaempferol represses TGF-β1-induced metastasis in lung cancer by inactivating AKT1-mediated phosphorylation of Smad3." (PMID 36874921, 2023).
lung carcinoma (continued). "A previous study used phosphorylated proteomics and found that MEK1 and AKT1/2 were abnormally activated in drug-resistant lung cancer cells compared with parent cells." (PMID 37513278, 2023). "AKT1 plays an important role in the development of lung cancer, Akt/protein kinase B signaling is very important for cancer cell survival and growth when cells are exposed to various apoptotic stimuli." (PMID 37623233, 2023). "High levels of PRMT5 expression in lung cancer have been associated with poor prognosis, and inhibition of PRMT5 can affect the growth cycle of lung cancer cells by inhibiting the phosphorylation of AKT1." (PMID 37400960, 2023). "High expression of AKT1, AKT2 and AKT3 was significantly associated with a OS in patients with clinical stage I lung cancer, and high expression of AKT3 was also found to be associated with a reduced OS in patients with clinical stage II lung cancer." (PMID 36945793, 2022). "In lung cancer, activation of Akt1/IL‐6/STAT3 pathway also contributes to maintaining the stemness of tumour initiating cells." (PMID 34997691, 2022). "It has been found that RHEBL1 is involved in sphingosylphosphorylcholine-induced events in A549 lung cancer cells via binding to AKT1 leading to activation of it." (PMID 36386821, 2022). "EGFR and AKT1 have been revealed to play a synergistic tumor-promoting role to aggravate tumor progression in human lung cancer." (PMID 35873484, 2022). "HSP90AA1, one of the HSP90 isoforms, showed a significant correlation with survival time in lung cancer patients by inhibiting the AKT1 and ERK pathways and was upregulated in colorectal cancer." (PMID 35957699, 2022). "Inhibition of PRMT5 can inhibit the phosphorylation of protein kinase AKT1, thereby affecting the growth cycle of lung cancer cells." (PMID 35531958, 2022). "A study has revealed that the expression of AKT1 protein is related to the differentiation degree of lung cancer, lymph node metastasis, and TNM stage." (PMID 36035842, 2022). "Luteolin has a good binding ability to AKT1, can inhibit the proliferation, invasion, and migration of nonsmall cell lung cancer (NSCLC) A549 cells, and can induce apoptosis." (PMID 36035842, 2022). "The higher levels of transcription and expression of HSP90AA1 and the activity of AKT1/ERK pathways were confirmed in lung cancer patient tissues." (PMID 35095481, 2021). "We then found that AKT1/ERK pathways were also significantly activated in these lung cancer tissues, suggesting a possible contribution of HSP90AA1 to their activation." (PMID 35095481, 2021). "As a result, we attempted to investigate the possible regulation of HSP90 on AKT1/ERK activation in lung cancer cells." (PMID 35095481, 2021). "17-DMAG inhibited cell proliferation and induced cell apoptosis in lung cancer cells by inhibiting the AKT1/ERK pathway, and it was well tolerated in normal cells and mouse models." (PMID 35095481, 2021). "As previously stated, high levels of AKT1/ERK pathways were commonly observed in lung cancers, which was confirmed in our study." (PMID 35095481, 2021). "Yang found that FBXW2 can participate in the occurrence and development of lung cancer by regulating epidermal growth factor-AKT1, β-catenin." (PMID 33029266, 2020). "In lung cancer, several studies have shown that miR-99a-5p acts as a tumor-suppressive miRNA by targeting critical oncogenic pathways, including AKT1 and mTOR signaling." (PMID 32932948, 2020).